EGR1 (early growth response 1)
Diseases named in the same sentence as EGR1 in open-access papers (continued):
Sharing a sentence is not in itself a finding about the gene and the disease.
astrocytoma (9 papers, 2009 to 2025). "The transcriptomic analysis shows that the components of the UPR-related genes such as PERK, ATF4, and DDIT3 (encoded CHOP) and early growth response 1 (EGR1) are activated in VEEV-infected human astrocytoma cells." (PMID 37946006, 2024). "EGR1 is upregulated in human astrocytoma cells infected with JCV and binds to the JCV late promoter to enhance viral transcription." (PMID 36338037, 2022). "Downregulation of diacylgycerol-regulated protein kinase C isoforms also impaired thrombin and carbachol-elicited expression of Egr-1 in 1321N1 astrocytoma cells." (PMID 19432968, 2009). "The most striking EGR1 dependency was observed in EEEV-infected astrocytoma cells." (PMID 35746681, 2022). "Hence, elevation of cytosolic Ca2+ levels is essential for induction of Egr-1 biosynthesis following thrombin and M1 or M3 muscarinic acetylcholine receptor stimulation in 39M1-81 fibroblasts or 1321N1 astrocytoma cells." (PMID 19432968, 2009). "In an effort to gain insight into genes that are differentially regulated through EGR1 activation or repression, our RNA-seq data from VEEV-infected human U87MG astrocytoma cells was leveraged." (PMID 35746681, 2022). "EGR1 was significantly upregulated to varying degrees in EEEV-, CHIKV-, RVFV-, SINV-, and ZIKV-infected astrocytoma cells." (PMID 35746681, 2022). "Early growth response 1 (EGR1) is an immediate early gene and transcription factor previously found to be significantly upregulated in human astrocytoma cells infected with Venezuelan equine encephalitis virus (VEEV)." (PMID 35746681, 2022). "Viral and host transcriptomic studies identified EGR1 as being highly upregulated after infection with encephalitic Venezuelan equine encephalitis virus (VEEV) in U87MG cells, a human astrocytoma cell line." (PMID 36338037, 2022). "Previous transcriptomic studies identified the immediate early gene (IEG) and transcription factor, early growth response 1 (EGR1), as being highly upregulated in U87MG astrocytoma cells in response to VEEV infection." (PMID 35746681, 2022). "Infection of the astrocytoma cells with EEEV resulted in a significant upregulation of transcription factors ATF3, FOS, and JUN, with both ATF3 and JUN being at least partially transcriptionally dependent on EGR1." (PMID 35746681, 2022). "Infection of astrocytoma cells with SINV, another Old World alphavirus, significantly induced transcription of CXCL10 and TNF-α, but neither were dependent on EGR1." (PMID 35746681, 2022).
COVID-19 (9 papers, 2020 to 2025). A disease caused by infection with severe acute respiratory syndrome coronavirus 2. "Of note, EGR1 was indicated as one of the most highly expressed transcription factors also in COVID-19 patients, representing one of the markers related to the first immune response to the infection." (PMID 39407208, 2024). "In COVID-19 interaction, the TF–miRNA network showed that E2F1, MAX, EGR1, YY1, and SRF were the highly expressed TFs, and hsa-miR-19b, hsa-miR-495, hsa-miR-340, hsa-miR-101, and hsa-miR-19a were among significant miRNAs." (PMID 36059456, 2022). "Ultimately, EEF1A1, EGR1, UBA52, DDX5 and IRF8 might be the key shared pathogenesis-related genes in COVID-19 and asthma." (PMID 36575422, 2022). "In addition, we identified a group of EGR1+ monocytes which can differentiate into pro-inflammatory CCL3+ monocytes, indicating the potential sources of systemic inflammation in COVID-19 patients." (PMID 36379915, 2022). "In COVID-19 patients, the DEG–miRNA, and DEG–transcription factors (TFs) interactions network analysis revealed that E2F1, MAX, EGR1, YY1, and SRF were the highly expressed TFs, whereas hsa-miR-19b, hsa-miR-495, hsa-miR-340, hsa-miR-101, and hsa-miR-19a were the overexpressed miRNAs." (PMID 36059456, 2022). "Notably, our identification of H3-5/H3F3C, H3C13/HIST2H3D, JUN, EGR1, NOTCH1, and SQSTM1/P62 as central hub genes unique to the COVID-19 signature links this pro-oncogenic state to a specific molecular target that regulates inflammation, autophagy, and cancer progression." (PMID 41472277, 2025).
Hyperinsulinemia (9 papers, 2015 to 2025). An increased concentration of insulin in the blood. "Mechanistically, EGR1 increases in response to hyperinsulinism subsequently activating GGDPS transcription." (PMID 36650113, 2023). "In COPD+NAFLD, the baseline metabolic milieu—characterized by hyperinsulinemia, elevated free fatty acids, and hepatic inflammation—likely sustains high EGR1 expression via MAPK/ERK and NF-κB activation, compounded by disruption of the liver-specific HNF4α/SHP regulatory axis." (PMID 40950963, 2025). "EGR1 responds to insulin stimulation, therefore GGDPS expression is sustained in response to hyperinsulinism eventually leading to insulin resistance." (PMID 36650113, 2023).
injury (9 papers, 2008 to 2024). Damage inflicted on the body as the direct or indirect result of an external force, with or without disruption of structural continuity. "To clarify the effect of PPARγ on Egr-1 expression in vivo, we first examine the production of Egr-1 during IgG-IC-induced acute lung injury." (PMID 33717177, 2021). "Egr1, a zinc-finger transcription factor of the immediate early gene family, plays a role in regulation of inflammation in cholestatic liver injury, ischemic and reperfusion lung injury, and atherogenesis." (PMID 29681936, 2018). "Interestingly, ethanol-elicited regulation of EGR-1 expression depends on the generation of acetaldehyde, and the absence of EGR-1 diminishes alcohol-induced liver injury." (PMID 33250767, 2020).
memory impairment (9 papers, 2015 to 2024). "Furthermore, decreased expression of EGR1, as seen in this study following iTBS, can be linked to improvement in STZ-induced memory impairment." (PMID 37273654, 2023). "This hypothesis fits well with observations that (a) the probability that the same GCs will consistently transcribe Egr1 in response to two exposures to similar (or even identical) stimuli is significantly lower in GKs, and (b) this inconsistency predicts memory impairment across individuals." (PMID 37397815, 2023).
osteoarthritis (9 papers, 2009 to 2024). A noninflammatory degenerative joint disease occurring chiefly in older persons, characterized by degeneration of the articular cartilage, hypertrophy of bone at the margins and changes in the synovial membrane. "Ferroptosis has vital effects on the development of osteoarthritis, and EGR1 has been identified as one of the possible diagnostic biomarkers based on bioinformatics analysis of ferroptosis-related genes." (PMID 38542784, 2024). "MiR-34-5P has been demonstrated to interact with ATF3, IL6, IL1B, and EGR1—an iron death-related gene identified in osteoarthritis (OA) synovial tissue—among others, potentially contributing to the pathogenesis of iron death." (PMID 39564502, 2024). "The role of EGR-1 in cartilage tissue and the mechanisms affecting osteoarthritis are unclear and controversial." (PMID 38912889, 2024). "Consistent with Egr1 expression in cartilage and bone, the Egr1 gene is reiteratively cited to be involved in chronic diseases that lead to articular cartilage degeneration, such as osteoarthritis and rheumatoid arthritis." (PMID 32121305, 2020). "Chondrocytes stimulation with interleukin-1β (IL-1) leads to the recruitment of EGR1 to Pparg promoter and downregulates its expression, preventing the protective effect of PPARγ in osteoarthritis." (PMID 32121305, 2020). "TNFα levels are increased in the synovial fluid of patients with osteoarthritis and rheumatoid arthritis and reduce the expression of Col2a1, Acan (Aggrecan), and Hapln1 through EGR1 recruitment to their promoters." (PMID 32121305, 2020). "Classical and global transcriptomic analysis identified high EGR1 expression in articular cartilage of patients with osteoarthritis and in synovial tissues of rheumatoid arthritis patients." (PMID 32121305, 2020). "The etiological involvement of EGR1 in osteoarthritis (OA) is, however, unclear, as both increased and decreased expression of EGR1 has been reported in the context of OA-cartilage." (PMID 23483971, 2013). "However, existing studies provide conflicting accounts regarding the expression and specific role of EGR-1 in osteoarthritis." (PMID 38912889, 2024). "Egr1 represents a potential target for drug intervention in osteoarthritis or rheumatoid arthritis." (PMID 32121305, 2020). "In particular, antagonizing MEK/ERK or activating Egr-1 may be useful methodologies for reversing cartilage degradation observed in both osteoarthritis and rheumatoid arthritis." (PMID 19144181, 2009). "Our results suggest that MEK/ERK and Egr1 are required for TNFα-regulated catabolic and anabolic genes of the cartilage extracellular matrix, and hence may represent potential targets for drug intervention in osteoarthritis or rheumatoid arthritis." (PMID 19144181, 2009). "Through bioinformatics analysis, eight hub genes (ATF3, EGR1, FOSB, FOSL1, FOSL2, JUN, JUNB, and MYC) were identified as potential regulators of osteoarthritis (OA) iron-death-related genes." (PMID 39564502, 2024).
prion disease (9 papers, 2008 to 2024). A transmissible disease that is caused by a protein that is able to induce abnormal folding of normal cellular proteins, leading to characteristic spongiform brain changes, which are associated with neuronal loss without an inflammatory response. "Of the 68 homeostatic microglial genes that are reduced in MGnD microglia, only one gene (Egr1) associated was significantly decreased during prion disease." (PMID 32381108, 2020). "Notably, studies performed on mouse brains suggest that prion diseases deregulate several microRNAs (miRNAs) and one of the gene promotors that were cognate to these miRNAs is Egr-1." (PMID 28066187, 2016). "Rbm3 upregulation combined with decreased Egr1 and Rab6b was readily detected at the clinical endpoint of prion disease, but not at earlier timepoints." (PMID 39580485, 2024). "EGR1 has been shown to share a disproportionate number of transcriptional targets with CREB1, also down-regulated in prion disease, suggesting that these two may be functionally related." (PMID 18987751, 2008). "Therefore, Egr1 is unlikely to influence apoptosis or pathogenesis during prion disease." (PMID 32381108, 2020).
Stroke (9 papers, 2014 to 2025). Sudden impairment of blood flow to a part of the brain due to occlusion or rupture of an artery to the brain. "Along with Fos and Jun, Cebpb, Ets2, Egr1, and Junb were enriched in Neut_Gngt2 and Neut_Cd14, particularly after stroke." (PMID 39930981, 2025). "In the context of other brain disorders, Egr1 has been shown to regulate the expression of the glial scar component phosphacan in astrocytes after experimental stroke, and to push neurodegeneration and neuroinflammation in a model for Parkinson’s disease." (PMID 35980567, 2024). "Similarly, studies conducted on Egr-1−/− mice have revealed that the inappropriate induction of Egr-1 is a contributing factor to inflammation and brain damage following a stroke." (PMID 38233877, 2024). "In hippocampal tissues, mRNA expression studies at 1 h and 24 h, and strongly elevated (Egr1, Akt1, Kras, Src, Foxo, Srf, Vegfr2, Nos3, Nos1) and decreased (Nos2, Nfkb) gene expression (Mapk1 not activated) also support BPC 157 beneficial effect on brain lesions, given in reperfusion in stroke-rats." (PMID 34203464, 2021).
acute myeloid leukemia (8 papers, 2008 to 2025). Acute myeloid leukemia (AML) is a group of neoplasms arising from precursor cells committed to the myeloid cell-line differentiation. "However, dysregulation of Egr1 is associated with hematological malignancies such as acute myeloid leukemia (AML), acute lymphoblastic leukemia (ALL), and chronic myelogenous leukemia (CML)." (PMID 35923847, 2022). "Egr1 is commonly deleted in the myelodysplastic syndrome (the acute myelogenous leukemia precursor condition), in mouse mutagenesis studies it induced myelodysplastic syndrome leukemogenesis, and acute myelogenous leukemia in mice was strongly associated with haploinsufficiency of Egr1." (PMID 19032775, 2008). "It promotes autophagy and proliferation of acute myeloid leukemia cells with mutant nucleophosphoprotein by regulating the expression of EGR1 and ULK3." (PMID 35299954, 2022). "Importantly, the EGR1 gene is located on chromosome 5, in a region that is often found to be deleted in acute myeloid leukemia (AML) cells." (PMID 35923847, 2022). "Fluorescence in situ hybridization (FISH) for adult acute myeloid leukemia (AML) and myelodysplastic syndromes (MDS) identified no mutations using probes 5p15.2 (D5S23, D5S721), 5q31 (EGR1), 7cen(D7Z1), 7q31 (D7S522), 8cen (D8Z2), 11q23 (MLL), 20q12 (D20S108), and 20q13.12 (D20S150)." (PMID 35280806, 2022). "Deletions in the 5q region, where Egr1 and several other tumor suppressor genes are mapped, is often observed in therapy-related myeloid neoplasms (t-MN), a subset of patients with primary myelodysplastic syndrome (MDS), and about 15% of patients with acute myeloid leukemia (AML) de novo." (PMID 29050203, 2017).
asthma (8 papers, 2015 to 2025). "Ovalbumin-induced asthma has been shown to be associated with an increased expression of early growth response 1 (Egr-1)." (PMID 38666929, 2024). "This disease-associated functional enrichment also revealed that EGR1 trajectory cluster component could be also implicated immune disorders principally such as autoimmune diseases, asthma, colitis, and arthritis." (PMID 34294125, 2021). "Collectively, our data suggested that HNG ameliorated airway inflammation in asthma partially due to NF-κB and Egr-1-mediated responses." (PMID 37451839, 2023). "Thus, a compound that suppresses the PKCδ/EGR-1 axis could be used as a therapeutic agent for treating asthma and COPD." (PMID 37108390, 2023). "However, the effects of Egr-1 on asthma have been less reported." (PMID 37451839, 2023). "Therefore, TLR4/NF-κB- and Egr-1- mediated inflammatory response and oxidative stress might be important therapeutic targets for asthma." (PMID 37451839, 2023). "Our results show that YPL-001 and its iridoids suppress the TNF/NF-κB/MUC5AC and PMA/PKCδ/EGR-1 cascades, which are important signaling pathways involved in inflammatory lung diseases, including COPD and asthma." (PMID 37108390, 2023). "Among the top genes are ones that have been previously related to asthma (e.g., APOE, CHI3L1, EGR1, MYH11, OXTR, SERPINB2, SOCS3) and corticosteroid-resistant asthma (e.g., FOS) though not necessarily in humans or via changes of the ASM." (PMID 26207385, 2015).
cervical cancer (8 papers, 2010 to 2024). A primary or metastatic malignant neoplasm involving the cervix. "Moreover, etoposide-induced BRCA1 promoter activity in cervical cancer cells was mediated by upregulated EGR1, which confirms the link between EGR1 and DNA damage repair." (PMID 38467631, 2024). "Interestingly, although Egr-1 acts as a transcriptional repressor of hTERT promoter-driven reporter constructs in cervical cancer cell lines, Egr-1 expression is elevated in hTERT positive cervical carcinomas." (PMID 20534141, 2010). "Thus also the repressive activity of Egr-1 may be inhibited by DNA methylation in cervical cancer cells and contribute to hTERT expression, because in approximately half of the alleles in the HPV-immortalized cell lines and cervical cancer cell lines, the Egr-1 site was methylated (CpG -42 - -46)." (PMID 20534141, 2010).
esophageal cancer (8 papers, 2013 to 2022). A primary or metastatic malignant neoplasm involving the esophagus. "Second, the activation of CXCR2 results in increased expression of early growth response-1 (EGR-1) in esophageal cancer, which increases proliferation by elevating the expression of cyclin-dependent kinase 4 (CDK4)." (PMID 35216283, 2022). "Egr-1 has been designated in the development of a spectrum of epithelia-derived tumors such as breast, prostate, colon, and esophageal cancers." (PMID 30400241, 2018). "Enhanced Egr-1 in esophageal cancer plays a significant part in facilitating advancement-associated oncogene/CXC chemokine receptor 2 proliferative signaling." (PMID 30400241, 2018). "EGR-1-related signaling in esophageal cancer may present potential target molecules for therapeutic intervention." (PMID 36233659, 2022). "In esophageal cancer, early growth response-1 (Egr-1) is a tumor suppressor gene, but the mechanism and associated genes are unknown." (PMID 36207572, 2022). "They investigated the relationship between the EGR-1 and esophageal cancer cells." (PMID 36233659, 2022). "Although EGR-1 is a crucial transcription factor in controlling cell growth, proliferation, differentiation, and angiogenesis, its role in the development of esophageal cancer is poorly understood despite the high frequency of this disease in many parts of the world." (PMID 36233659, 2022). "The CXCL1/CXCR2 axis has been shown to participate in the regulation of ERK1/2 phosphorylation in esophageal cancer, which is responsible for the transcription of the EGR-1 gene, the crosstalk of among CXCL1/CXCR2 axis, ERK1/2 and EGR-1 result in a rapid increase in tumor cell proliferation." (PMID 35764974, 2022). "The relationship between EGR-1 expression and eukaryotic translation initiation factor 4E-binding protein 1 (4E-BP1) gene expression in esophageal cancer cells has been investigated." (PMID 36233659, 2022). "The EGR-1 expression was reported to increase in TE2 esophageal cancer (TE2) cells compared with other esophageal cell lines, and knockdown of EGR-1 could increase 4E-BP1 expression in TE2 cells, which became sensitive to rapamycin treatment." (PMID 36233659, 2022).
prostate tumor (8 papers, 2010 to 2025). "report that the increased circCSPP1 in PCa, which is catalyzed by HnRNP-L, can induce cellular autophagy through the circCSPP1-miR-520h-EGR1 axis, leading to the progression of prostate tumor." (PMID 34760337, 2021). "For example, EGR1 expression is higher in a prostate tumor than in surrounding prostate tissue, and the expression of EGR1 in the prostate tumor positively correlates with malignancy." (PMID 33842351, 2021). "Although EGR1 has previously been reported to be elevated in high grade prostate tumors (GS 8-10), our results demonstrated that EGR1 expression was not significantly elevated in tumor tissues relative to non-neoplastic tissues in paired T3 stage samples." (PMID 20426842, 2010). "EGR1, which may promote aggressiveness in prostate tumors, but appears protective against tumor progression in other cancer types, also showed lower expression in recurrence patients." (PMID 40691608, 2025). "To determine if increased nuclear localization of EGR1 leads to changes in the expression of genes it regulates in EBV-positive cells, we considered candidates identified previously by ChIP-on-ChIP assays performed in prostate tumor cells." (PMID 33664726, 2021).